SMARCE1 (SWI/SNF related BAF chromatin remodeling complex subunit E1)
Diseases named in the same sentence as SMARCE1 in open-access papers (continued):
Sharing a sentence is not in itself a finding about the gene and the disease.
breast carcinoma (10 papers, 2009 to 2025). "Chromatin remodelling complex protein, SMARCE1 (a target of miR-1266-5p) which was overexpressed (1.64 fold; p-value ≤ 0.05) in tobacco treated cells has been associated with both breast cancer invasion and metastasis in ovarian cell carcinoma." (PMID 29728663, 2018). "By analyzing the expression data of 3554 breast tumor samples collected by an online Kaplan-Meier survival analysis tool, we found that higher expression of SMARCE1 or PTK2 is associated with shorter interval of relapse-free survival (RFS) of breast cancer patients." (PMID 27495308, 2016). "We selected the transcription factor SMARCE1 as our candidate therapeutic target, which was previously identified as a key driver of invasive progression of early-stage breast cancer." (PMID 38437557, 2024). "We first demonstrate that similar to breast cancer, shRNA-mediated knockdown of SMARCE1 in ovarian cancer leads to decreased tumor growth by downregulation of invasive proteases." (PMID 38437557, 2024). "Our therapeutic target is the transcription factor SMARCE1, which was previously identified as a key driver of invasion in early-stage breast cancer." (PMID 38437557, 2024). "Upregulated mSigDB modules include pathways typically associated with breast cancer invasiveness, including SMARCE1 targets (p-value 2.6E−16), ESR1 targets (p-value 5.3E−16), and a comparison of luminal and mesenchymal breast cancers (p-value 2.1E−12)." (PMID 33413550, 2021). "SWI/SNF-related matrix-associated actin-dependent regulator of chromatin subfamily E member 1 (SMARCE1) is known to play an essential role in breast cancer metastasis by protecting cells against anoikis through the HIF1A/PTK2 pathway." (PMID 29728663, 2018). "Genetic approaches and chemical inhibitors were used to manipulate the activities of SMARCE1 and its downstream targets in multiple breast cancer cell lines." (PMID 27495308, 2016). "Our in vivo experiment results implicate that SMARCE1 plays an essential role in distant metastasis of breast cancer cells by promoting the survival of circulating tumor cells." (PMID 27495308, 2016). "This study is aimed to characterize the role of SMARCE1/BAF57 in regulating metastasis of breast cancer cells." (PMID 27495308, 2016). "Together, these results suggest that activation of PTK2, ERK, and AKT pathways is critical for breast cancer cells to survive anoikis, and SMARCE1 activity is required for the activation of these survival pathways in detached cells." (PMID 27495308, 2016). "Our study provides evidence suggesting an essential role of SMARCE1-based chromatin remodeling activity in breast cancer metastasis by facilitating HIF1A-mediated PTK2 transcription activation in detached cells under normoxia." (PMID 27495308, 2016). "SMARCE1 knockdown reduced lung metastasis of breast cancer cells and sensitized tumor cells to anoikis." (PMID 27495308, 2016). "In this study, we demonstrated that SMARCE1 plays a key role in breast cancer metastasis by protecting breast cancer cells against anoikis through the HIF1A/PTK2 pathway." (PMID 27495308, 2016). "SMARCE1 plays an essential role in breast cancer metastasis by protecting cells against anoikis through the HIF1A/PTK2 pathway." (PMID 27495308, 2016). "Public databases were used to investigate the relationship between SMARCE1 deregulation and breast cancer prognosis." (PMID 27495308, 2016). "This study establishes a novel role of SMARCE1 in regulating metastatic potential of breast cancer cells by promoting survival of detached cells through the HIF1A/PTK2 pathway." (PMID 27495308, 2016). "One set that was present in their data set after SMARCB1 reactivation and in 2 of our cell lines, CHLA02 and CHLA05, after combination treatment was “WANG_SMARCE1_TARGETS_UP,” which represents genes that are upregulated in breast cancer with reintroduction of SMARCE1, another component of SWI/SNF." (PMID 41408661, 2025).
breast carcinoma (continued). "To determine whether SMARCE1-mediated anoikis resistance can be extended to other breast cancer cell lines, we examine the effect of SMARCE1 knockdown in HCC38, a triple-negative breast cancer cell line." (PMID 27495308, 2016). "According to the database of Project Achilles that performed genome-wide pooled shRNA screens across hundreds of cancer cell lines to identify genes essential for tumor cell proliferation, SMARCE1 knockdown showed limited effect on proliferation of breast cancer cells." (PMID 27495308, 2016). "While the interrelation between GR and SMARCE1 and ARID1A in breast cancer has not been clearly evaluated yet, both SWI/SNF subunits were associated with breast cancer metastasis and breast cancer patient survival." (PMID 35761157, 2022).
Clear Cell Meningioma (10 papers, 2021 to 2025). A WHO grade II morphologic variant of meningioma characterized by the presence of clear glycogen-rich polygonal cells. "In line with our data, clear cell meningioma harboring a SMARCE1 mutation have been commonly described in children and young adults." (PMID 33319313, 2021). "All SMARCE1 alterations were present in clear-cell meningiomas (mutations in 5/7 tumors detected)." (PMID 34495383, 2021). "A rare cancer called clear cell meningioma (CCM) is marked by the biallelic inactivation of the SMARCE1/BAF57 gene." (PMID 39471843, 2024). "Thus, SMARCE1 has been suggested as the potential oncogenic driver in clear cell meningioma." (PMID 33319313, 2021). "We report the first case of multiple nondura-based clear cell meningiomas without SMARCE1 expression at the lumbar spine 7 years after resection of intracranial CCM." (PMID 38321548, 2024). "Importantly, it has been recently demonstrated that in clear cell meningioma (CCM), driven by loss of SMARCE1, the cBAF complex fails to stabilize on chromatin, attenuating its activity." (PMID 38883782, 2024).
Intellectual disability (6 papers, 2016 to 2023). "Previous study showed SMARCE1 to be associated with the occurrence and development of non-syndromic intellectual disability." (PMID 30349449, 2018). "SMARCA2-ATPase mutations result in severe intellectual disability cases of NCBRS, but SMARCE1-HMG and DPF2-PHD mutations are correlated to moderate-severe and mild intellectual disability phenotypes, respectively." (PMID 37500730, 2023).
ovarian carcinoma (4 papers, 2018 to 2024). A malignant neoplasm originating from the surface ovarian epithelium. "Using a doxycycline-inducible shRNA knockdown in OVCAR8 ovarian cancer cells both in vitro and in vivo, we demonstrate that SMARCE1 is a master regulator of genes encoding proinvasive proteases in a model of human ovarian cancer." (PMID 38437557, 2024). "SMARCE1 promotes dissemination of ovarian cancer through regulating the expression of secreted proteases that degrade the ECM." (PMID 38437557, 2024). "The overall survival of ovarian cancer patients with high expression levels of SMARCE1 was more likely to show relapse with metastases over a follow-up period of more than 15 y [n = 1,435, hazard ratio (HR) = 1.19, P = 0.019]." (PMID 38437557, 2024). "In light of the findings that SMARCE1 promotes ovarian cancer invasion in vitro, we next assessed the in vivo function of SMARCE1 by using an orthotopic mouse model of OVCAR8-derived tumor formation." (PMID 38437557, 2024). "In an orthotopic ovarian cancer xenograft model, theranostic nanoparticles were able to knockdown SMARCE1 which was in turn reported through a reduction in protease-activated urinary reporters." (PMID 38437557, 2024). "In conclusion, lncRNA HOTTIP modulates the miR-615-3p/SMARCE1 pathway, thereby enhancing ovarian cancer growth and metastasis." (PMID 37854681, 2023). "Specifically, the forced over‐expression of SMARCE1 in ovarian cancer cells induces the secretion of IL8, MIP1b and CCL5 chemokines in the supernatant and triggers the chemotaxis of CD8 + lymphocytes in a cell culture assay." (PMID 32162380, 2020). "We chose to use the PLGVRGK substrate as a candidate self-reporting readout sensor to detect broad MMP protease activity because this peptide has shown efficacy in tracking progression of ovarian cancer models and exhibited strong reduction in cleavage signal following SMARCE1 knockdown." (PMID 38437557, 2024). "Finally, we demonstrate that LbL NPs can quantify protease activity in response to reduction of SMARCE1 in vivo, thus resulting in a pharmacodynamic reporter of siRNA delivery and efficacy in ovarian cancer." (PMID 38437557, 2024). "We demonstrate that SMARCE1 is a relevant siRNA target for early-stage ovarian cancer." (PMID 38437557, 2024). "However, the functional contribution of SMARCE1 to the invasion of ovarian cancer and its regulatory impact on proteolytic activity remain understudied." (PMID 38437557, 2024). "We next investigated the functional impact of SMARCE1 in ovarian cancer progression." (PMID 38437557, 2024). "SMARCE1 Expression Correlates with Survival Outcome in Patients with Early-stage Ovarian Cancer." (PMID 38437557, 2024). "Either the upregulation of miR-615-3p or the downregulation of SMARCE1 could abrogate the tumor-promoting effect of HOTTIP in ovarian cancer." (PMID 37854681, 2023). "In addition, a study on ovarian cancer using differential expression analysis discovered that SMARCE1 mRNA levels are closely correlated with the number of intra‐tumoral CD8+ cells." (PMID 32162380, 2020). "Additionally, previous studies have suggested knockdown of SMARCE1 sensitizes ovarian cancer to chemotherapy treatment, and thus testing a combination treatment with carboplatin or paclitaxel, the current regimen of ovarian cancer chemotherapy treatment, may optimize tumor regression." (PMID 38437557, 2024). "We performed immunostaining for SMARCE1 protein in human ovarian cancer tissue microarrays (Left) and observed that SMARCE1 was not detectable or expressed at very low levels in normal tissue and early-stage ovarian cancer." (PMID 38437557, 2024). "In contrast, SMARCE1 expression was not predictive of survival for patients diagnosed with later-stage ovarian cancer tumors (stages III and IV) (n = 1,268, HR = 1.093, P = 0.286) (Bottom)." (PMID 38437557, 2024).
ovarian carcinoma (continued). "However, in tumor samples from late-stage ovarian cancer patients (III, Mets), SMARCE1 expression increased and was highest in tumors invading into regional lymph nodes and distant organs." (PMID 38437557, 2024).
spinal meningioma (3 papers, 2020 to 2023). Spinal meningioma isa rare type of spinal cord cancer. "In addition, genes encoding tumour‐associated subunits of the SWI/SNF complex, such as BAF57/SMARCE1, are heterozygous for mutations or completely lost in familial spinal meningioma cases." (PMID 36883311, 2023).
hepatocellular carcinoma (2 papers, 2019 to 2020). A malignant tumor that arises from hepatocytes. "Previous studies have pointed out that miR-29a promotes hepatitis B virus (HBV) replication and expression by targeting SMARCE1 in hepatocellular carcinoma, and miR-204 and miR-126 inhibit HBV replication via two distinct mechanisms." (PMID 32674073, 2020).
Obesity (2 papers, 2018 to 2021). Accumulation of substantial excess body fat. "MAP 1B, hsa-mir-4314, hsa-mir-5688, hsa-mir-583, hsa-mir-632, hsa-mir-3176, hsa-mir-4477a, hsa-mir-606, hsa-mir-1343-3p6, SIN3A, ZNF143 and SMARCE1 are the novel biomarkers for pathogenesis of obesity associated type 2 diabetes mellitus." (PMID 33902539, 2021). "We replicated the associations of rs6598860 (P = 0.04) in ARID1A and rs17003998 in SMARCE1 (P = 0.01) with overweight/obesity." (PMID 29500370, 2018).
Alzheimer disease (1 paper, 2018). A progressive, neurodegenerative disease characterized by loss of function and death of nerve cells in several areas of the brain leading to loss of cognitive function such as memory and language. "PANTHER pathways analysis of differentially expressed proteins revealed overrepresentation of Wnt signaling pathway (CDH1, CSNK2A2, GNA11, CTBP2, CDH17, SMARCE1, p-value 0.02), followed by Alzheimer disease-presenilin pathway (MMP8, MMP9, MLLT4, CDH1, P-value 0.04)." (PMID 29515771, 2018).
BAFopathy (1 paper, 2022). Disorder caused by mutations in the various subunits composing the BAF complex. "Typical CSS, which is also referred to as BAFopathy, is caused by variants in the subunit of BAF complex, including ARID1A (OMIM#603024), ARID1B (OMIM#614556), SMARCA4 (OMIM#603254), SMARCB1 (OMIM#601607), ARID2 (OMIM#609539), and SMARCE1 (OMIM#603111)." (PMID 35938035, 2022).
breast tumors (1 paper, 2016). "Our findings are likely relevant to basal-like and luminal B breast tumors, because a positively correlated expression between SMARCE1 and PTK2 is evident in these subtypes of tumors." (PMID 27495308, 2016). "Expression data analysis of a large cohort of human breast tumors revealed that high expression of SMARCE1 or PTK2 is associated with poor prognosis and tumor relapse, and PTK2 expression is positively correlated with SMARCE1 expression in basal-like and luminal B subtypes of breast tumors." (PMID 27495308, 2016). "SMARCE1-mediated PTK2 activation likely plays a key role in promoting metastasis of basal-like and luminal B subtype of breast tumors." (PMID 27495308, 2016). "Next, we examined the relationship between the expression of SMARCE1 and PTK2 in breast tumors in The Cancer Genome Atlas (TCGA) database." (PMID 27495308, 2016).
dermatitis (1 paper, 2021). An inflammatory process affecting the skin. "Variants at ARRCD1 and CCR7/SMARCE1 were previously identified in a study on the broader phenotype “dermatitis or eczema” in UKBB18." (PMID 34785669, 2021).
ear malformation (1 paper, 2024). "Compared with the overall CSS patients, the reported SMARCE1-related CSS patients had a higher incidence of otolaryngologic features including palate abnormalities, feeding difficulties, and ear malformations." (PMID 39906730, 2024).
eczema (1 paper, 2021). "Even variants with an imputation quality r2 < 0.8 confirmed association results at known eczema loci (FLG, ARRCD1, CCR7/SMARCE1)." (PMID 34785669, 2021).
gastric adenocarcinoma (1 paper, 2023). "According to the boxplot analysis, the mRNA levels of DOCK4, GNAS, TGFB1, SELE, and SMARCE1 demonstrated a considerably higher expression in gastric adenocarcinoma than in healthy controls." (PMID 37037466, 2023).
gastric cancer (1 paper, 2023). A primary or metastatic malignant neoplasm involving the stomach. "Expression of SMARCA4 and SMARCE1 in gastric cancer as illustrated by immunohistochemistry." (PMID 36916408, 2023).
glaucoma (1 paper, 2021). Increased pressure in the eyeball due to obstruction of the outflow of aqueous humor. "Finally, a GWAS study would be of interest to explore the potential role of Tns4 and Smarce1 as risk factors in human presentations of glaucoma, myopia, and/or keratoconus." (PMID 33634081, 2021). "This work motivates further study of Smarce1 and Tns4 for their role(s) in ocular pathology involving the corneoscleral envelope as well as the development of novel mouse models of ocular pathophysiology, such as myopia and glaucoma." (PMID 33634081, 2021). "Thus, Smarce1 and/or T are excellent candidates for further investigation for their potential role(s) in affecting corneoscleral stiffness, of interest in glaucoma, myopia, and keratoconus." (PMID 33634081, 2021).
lung adenocarcinoma (1 paper, 2021). A carcinoma that arises from the lung and is characterized by the presence of malignant glandular epithelial cells. "For this, we made use of a GR activity score (explained above) and the lung adenocarcinoma dataset from TCGA (91/877 tumours harboured SWI/SNF mutations; SMARCB1 18.09%; SMARCC2 9.52%, SMARCD2 6.66%, SMARCD3 1.90%, ARID1A 29.52%, ARID2 31.42%, SMARCE1 2.85%)." (PMID 34272384, 2021).
lung carcinoma (1 paper, 2016). "It was reported recently that EGFR expression is regulated by SMARCE1, SMARCA4, and ARID1A and that SMARCE1 deficiency confers TKI resistance in lung cancer." (PMID 27783942, 2016).
microphthalmia (1 paper, 2023). Congenital or developmental anomaly in which the eyeballs are abnormally small. "Furthermore, the SMARCE1 knockout zebrafish suggested the involvement of SMARCE1 in NCC differentiation, as the microphthalmia phenotype in SMARCE1-deficient embryos might indicate disruption of the NCC deriving process." (PMID 36895044, 2023).
myopia (1 paper, 2021). "Additionally, Tns4 and Smarce1 signaling could be evaluated after form deprivation-induced myopia in wild type mice." (PMID 33634081, 2021).
non-small cell lung carcinoma (1 paper, 2024). A group of at least three distinct histological types of lung cancer, including non-small cell squamous cell carcinoma, adenocarcinoma, and large cell carcinoma. "Additionally, SMARCE1 is involved in gene transcription repression in non-small cell lung cancers (NSCLCs)." (PMID 39162221, 2024).
ovarian tumors (1 paper, 2024). "In particular, patients with early-stage (I and II) ovarian tumors expressing high levels of SMARCE1 showed significantly lower probability of survival (n = 179, HR = 1.19, P =0.019) (Top)." (PMID 38437557, 2024).
schwannomatosis (1 paper, 2023). The least frequent form of the rare genetic disorder neurofibromatosis. "Schwannomatosis-like disorders are rare disorders that share clinical and genetic features with schwannomatosis but are caused by mutations in the SMARCE1 gene." (PMID 37240461, 2023).
Sézary syndrome (1 paper, 2023). "Other SWI/SNF genes recurrently altered in CTCLs are SMARCE1 and SMARCD2 (each amplified in 20% Sézary syndrome patients, N = 25), ARID2 (deleted in 8% Sézary syndrome patients, N = 25), and SMARCB1 (point mutation frequency ~ 3%, combined N = 433)." (PMID 36810086, 2023).
skin cancer (1 paper, 2021). "RIP assay in A375 cells provided confirmation that SMARCE1 also could bind to cyclin D1 pre-mRNA, indicating the important role of SMARCE1 in regulating the alternative splicing of cyclin D1 gene in skin cancer cells." (PMID 33670012, 2021).
skin melanoma (1 paper, 2021). "We also examined the influences of mechanical strain and SMARCE1 overexpression on the splicing of cyclinD1 in skin melanoma A375 cells and found that mechanical stimulation and SMARCE1 both could increase the cyclinD1a and cyclinD1b expression." (PMID 33670012, 2021).
triple-negative breast carcinoma (1 paper, 2016). An invasive breast carcinoma which is negative for expression of estrogen receptor (ER), progesterone receptor (PR), and human epidermal growth factor receptor 2 (HER2). "In addition, we examined the effect of SMARCE1 overexpression in BT549, a triple-negative breast cancer cell line that lacks SMARCE1 expression due to a biallelic inactivating mutation that causes a frameshift." (PMID 27495308, 2016).
viral infection (1 paper, 2025). "PBRM1 is a chromatin modulator of the SWI/SNF chromatin remodeling complex, which includes SMARCA4, SMARCB1, SMARCC1, ARID1A, DPF2, and SMARCE1, also implicated in ACE2 expression regulation and, thus, in host cell susceptibility to viral infection." (PMID 40378209, 2025).